CDK2 (cyclin dependent kinase 2)
Diseases named in the same sentence as CDK2 in open-access papers (continued):
Sharing a sentence is not in itself a finding about the gene and the disease.
follicular lymphoma (1 paper, 2013). Follicular lymphoma is a form of non-Hodgkin lymphoma characterized by a proliferation of B cells whose nodular structure of follicular architecture is preserved. "Aggressive follicular lymphoma, a subset of NHL, is associated with upregulation of genes involved in cell cycle control such as CCNE2 (cyclin E2), CCNA2 (cyclin A2), CDK2 (cyclin-dependent kinase 2), and genes-reflecting increased metabolism and DNA synthesis." (PMID 23533401, 2013).
gastric diseases (1 paper, 2020). "TGF-β-SMAD3 can inhibit CDK2 to promote Treg differentiation, which indicates that the immune microenvironment may play an essential role in the gastric diseases." (PMID 33282942, 2020).
germ cell tumor (1 paper, 2015). A benign or malignant, gonadal or extragonadal neoplasm that originates from germ cells. "Elevated expression of cyclin A2 and their catalytic partners CDK1 and CDK2 have been detected in male germ cell tumors, and their levels are quantitatively associated with tumor invasiveness." (PMID 25782154, 2015).
glaucoma (1 paper, 2023). Increased pressure in the eyeball due to obstruction of the outflow of aqueous humor. "On the other hand, Cdkn2c (cyclin-dependent kinase inhibitor 2c) was upregulated in the UON at the three day crush time point, and Cdkn3 (cyclin-dependent kinase inhibitor 3), which prevents the activation of Cdk2, was also increased in early glaucoma in this same region." (PMID 37762022, 2023).
Glucose intolerance (1 paper, 2018). Glucose intolerance (GI) can be defined as dysglycemia that comprises both prediabetes and diabetes. "Indeed, mice lacking Cdk2 are viable and targeted Cdk2 deletion in the pancreas induces glucose intolerance primarily by affecting glucose-stimulated insulin secretion." (PMID 30300385, 2018).
Hepatitis (1 paper, 2020). Inflammation of the liver.
hyperphosphatemia (1 paper, 2011). Abnormally high level of phosphate in the blood. "While simulated hyperphosphatemia led to a decrease in the level of cyclin D3, simulated hypophosphatemia led to an increase in the level of CDK2 in HUVECs." (PMID 21858050, 2011).
Hypertension (1 paper, 2019). The presence of chronic increased pressure in the systemic arterial system. "Knocking down MRAK048635_P1 promoted the expression of these cycle-related markers, suggesting that low level of MRAK048635_P1 might enhance the proliferation of VSMCs via regulating cyclinD1/E, CDK2/4, and p-Rb in hypertension." (PMID 30833363, 2019).
Hypoglycemia (1 paper, 2023). A decreased concentration of glucose in the blood. "The purpose of this docking was to investigate whether the primary bioactive constituents of the compound played a role in hypoglycemia through the compound's key targets, which were CDK2, E2F1, CDKN1A, CDK1, and CCND1 and CCNB1." (PMID 36846049, 2023).
hypophosphatemia (1 paper, 2011). Lower than normal levels of phosphates in the circulating blood.
immune thrombocytopenia (1 paper, 2022). "Bosutinib is an inhibitor of CDK2 for chronic granulomatous leukemia treatment, and fostamatinib is an inhibitor of AURKB for persistent/chronic adult immune thrombocytopenia treatment." (PMID 36105485, 2022).
lentivirus infection (1 paper, 2022). Virus diseases caused by the Lentivirus genus. "We then introduced either exogenous wild-type (WT) CDK2 or mutant CDK2-3As in the THP1 CDK2−/− cells by lentivirus infection, named as THP1 CDK2-wt cells and THP1 CDK2-3As cells, respectively." (PMID 35595767, 2022).
liver diseases (1 paper, 2022). "Roscovitine (a Cdc2, CDK2, and CDK5 inhibitor) protects against liver diseases by inhibiting macrophage inflammatory actions and HSC activation at the onset of liver injury." (PMID 36313366, 2022).
Lynch syndrome (1 paper, 2013). An autosomal dominant hereditary neoplastic syndrome characterized by the development of colorectal carcinoma and a high risk of developing endometrial carcinoma, gastric carcinoma, ovarian carcinoma, renal pelvis carcinoma, and small intestinal carcinoma. "Lynch syndrome tumors showed up-regulation of 1129 genes, e.g. genes involved in G1/S transition (CCNE, CCNH, E2F2 and CDK2), DNA replication (CDC45, RPA1, RFC5, MCM4 and POLD3) and chromosomal organization and mitosis (CCNB2, MLF1IP, CASC5, KIF2C and PLK4), which is in line with previous findings." (PMID 23951239, 2013).
malignant glioma (1 paper, 2019). A grade III or grade IV glioma arising from the central nervous system. "As a CNV-driven ceRNA, CDKN2B has been reported to serve as a functional unit in the oncogenesis of malignant gliomas, its ceRNA pairs, CDK2 and RBL1, were also annotated in cell cycle and located in the downstream of the pathway." (PMID 31719831, 2019).
malignant mesothelioma (1 paper, 2023). A malignant neoplasm of the pleura or peritoneum, arising from mesothelial cells. "The other subunit of ferritin, the ferritin light chain (FTL), is able to affect p27, p21, cyclin-dependent kinase 2 (CDK2), and retinoblastoma protein (pRB) expression, increasing the proliferative capacity of malignant mesothelioma cells and promoting the cell cycle." (PMID 37626858, 2023).
metabolic syndrome (1 paper, 2016). A cluster of metabolic risk factors for CARDIOVASCULAR DISEASES and TYPE 2 DIABETES MELLITUS. "Nineteen high-frequency targets were obtained and mainly related to cancer and metabolic syndrome, especially CDK2 and PPAR γ." (PMID 27213329, 2016).
metastatic disease (1 paper, 2022). "Cox proportional hazard regression analysis of PFS according to the signatures of CDK6, p-CDK2 and cyclin E1 and clinicopathological parameters of the metastatic disease showed that the combined biomarkers signature was an independent prognostic factor of PFS in both tested cohorts." (PMID 36153348, 2022).
monocytic leukemia (1 paper, 2010). "We found that celastrol could arrest human monocytic leukemia cells U937 at G0/G1 phase, this arrest accompanied by down-regulation of Cyclin D1, Cdk4, Cdk6, and Cdk2." (PMID 20398364, 2010).
myopia (1 paper, 2024). "In the present study, continuous myopia induction will lead to increased CDK2 expression, and this continuous external stimulation causes sustained DNA damage to the retina." (PMID 38807184, 2024).
Nijmegen breakage syndrome (1 paper, 2012). Nijmegen breakage syndrome is a rare genetic disease presenting at birth with microcephaly, dysmorphic facial features, becoming more noticeable with age, growth delay, and later-onset complications such as malignancies and infections. "We identified Nbs1, product of the gene mutated in the cancer-predisposing Nijmegen Breakage Syndrome, as a Cdk2 substrate and showed that mutant forms of Nbs1 that cannot be modified by Cdk2 are defective in protecting cells from death due to IR–induced DNA damage." (PMID 22927831, 2012).
pancreatitis (1 paper, 2022). Inflammation of the pancreas. "Pancreatitis mice displayed an increased expression on IL‐23 and a decreased expression of Cdk2." (PMID 35634959, 2022). "Then, using shRNA or CDKs inhibitor to knockdown Cdk2 could induce the expression of IL‐23, which suggested that Cdk2 negatively regulated IL‐23 expression in LPS‐treated RAW 264.7 cells as well as the severity of pancreatitis." (PMID 35634959, 2022).
parasite infection (1 paper, 2024).
parvovirus infection (1 paper, 2024). "It has been elucidated that the disintegration of the nuclear envelope induced by parvovirus infection involves a sequential enzymatic cascade mediated by PKC, CDK2, and caspase-3." (PMID 39602452, 2024).
Pca (1 paper, 2020). "The protein expression levels of CDK2, CDK4, CDK6, and phospho-Rb (Ser807/811) declined in quiescent Pca cells, and almost all of them began to recover at 12 and 16 h after quiescent LNCaP and PC-3 cell re-entry into the cell cycle, respectively." (PMID 33392189, 2020).
pineal tumor (1 paper, 2012).
salivary gland cancer (1 paper, 2021). A primary or metastatic malignant neoplasm that affects the major or minor salivary glands. "Further, using CDK5 siRNA, we show that salivary gland cancer cell lines are sensitive to inhibition of CDK5 as a function of LMW-E expression, but independent of CDK2 status." (PMID 33990543, 2021).
salivary gland tumors (1 paper, 2021). "Here, we report that LMW-E can also drive the initiation of salivary gland tumors (SGTs), but independently of CDK2 status." (PMID 33990543, 2021).
scleroderma (1 paper, 2025). Scleroderma is a rare autoimmune connective tissue disorder characterized by abnormal hardening of the skin and, sometimes, other organs. "In conclusion, our study provides new evidence that esomeprazole exerts anti-proliferative effects on scleroderma fibroblasts by inducing cell cycle arrest through p21 upregulation and CDK1 and CDK2 downregulation." (PMID 41567630, 2025).
serous ovarian tumors (1 paper, 2017). "CCNE1 amplification, occurring in ∼20% of the high grade serous ovarian tumors, was previously proposed as a marker for platinum resistance and poor prognosis as well as for CDK2 inhibition." (PMID 28977941, 2017).
soft tissue sarcoma (1 paper, 2014). A malignant neoplasm arising from muscle tissue, adipose tissue, blood vessels, fibrous tissue, or other supportive tissues excluding the bones. "In vitro investigation of soft tissue sarcoma cells has shown that cdk2 decrease combined with p27 loss affects the cellular invasion program." (PMID 25136960, 2014).
sterility (1 paper, 2020). "Despite this role of CDK2 in cell division, unexpectedly two different CDK2 knockout mouse models have a fully penetrant phenotype of sterility with otherwise normal development and lifespan, but a slightly smaller size after weaning." (PMID 32543655, 2020).
T-cell leukemia (1 paper, 2022). A malignant disease of the T-lymphocytes in the bone marrow, thymus, and/or blood. "Pimozide, an inhibitor of USP1, results in the arrest of adult T-cell leukemia cells in the G1 phase, leading to the accumulation of p21 and p27 and reduction in the protein levels of cyclin D2, cyclin E, CDK2, CDK4, and CDK6." (PMID 36357365, 2022).
tongue cancer (1 paper, 2025). A malignant neoplasm affecting the tongue. "Red rectangles represent the hit genes involved in the treatment of tongue cancer (TERT, Bcl-2, CDK4/6, CDK2, VEGF, ER, RXR,c-KIT, MET, FGFR, PPAR8, PFFP, MMPs, CDK4, AR, F2, IGFR)." (PMID 39863836, 2025). "Those hub genes involved in pathways of cancer are Bcl2, EGFR, ESR1, MMP9, PPARG, and MMP2 and those involved in PI3K-Akt signaling pathways are Bcl2, EGFR, CDK2, and MCL1 these genes are considered therapeutic targets for tongue cancer." (PMID 39863836, 2025).
tongue squamous cell carcinoma (1 paper, 2020). A squamous cell carcinoma that arises from the tongue. "In Tongue Squamous Cell Carcinoma (TSCC) cells, PRR11 can promote proliferation and invasion by regulating p21, p27, CDK2, and Cyclin A to facilitate S phase progression." (PMID 32180800, 2020).
type 1 diabetes (1 paper, 2016). "We found that treatment of podocytes with sera from normoalbuminuric type 1 diabetes patients with high lipopolysaccharide (LPS) activity, known to predict progression of DN, downregulated CDK2 (cyclin-dependent kinase 2)." (PMID 26876672, 2016).
ulcerative colitis (1 paper, 2026). An inflammatory bowel disease involving the mucosal surface of the large intestine and rectum. "For example, it is reported that the inflammatory region of ulcerative colitis exhibits highly active CDK2." (PMID 41511373, 2026).
Uterine leiomyoma (1 paper, 2019). The presence of a leiomyoma of the uterus. "In agreement with our results, Kim and colleagues reported that ISL induces uterine leiomyoma cell cycle arrest, the activation of caspase-3, and the down-regulation of Bcl-2, CDK2/4, and E2F protein expression levels." (PMID 31394829, 2019).
uveitis (1 paper, 2013). An inflammatory process affecting a part of or the entire uvea. "This study also suggests that inhibition of CdK2 and other potential CdKs is a promising strategy to treat uveitis and other T cell-mediated diseases." (PMID 24260551, 2013).
Vestibular schwannoma (1 paper, 2018). A vestibular schwannoma (also known as acoustic neuroma, acoustic neurinoma, or acoustic neurilemoma) is a benign, usually slow-growing tumor that develops from the VIIIth cranial nerve supplying the inner ear. "In a study of vestibular schwannoma patients, CDK2 was primarily localized in the vestibular nerve, and Schwann cells, axons, and ganglion cells had high CDK2 expression, which indicates that CDK2 is related to the slow growth rate of these tumor." (PMID 29760650, 2018).
vitamin D deficiency (1 paper, 2015). A nutritional condition produced by a deficiency of VITAMIN D in the diet, insufficient production of vitamin D in the skin, inadequate absorption of vitamin D from the diet, or abnormal conversion of vitamin D to its bioactive metabolites.
Zinc deficiency (1 paper, 2017). A deficiency of the essential metal Zinc; an essential cofactor for many enzymes. "The cell cycle regulator p21 was cleaved by caspase 3 during zinc deficiency, activating cyclin-dependent kinase 2 (CDK2)." (PMID 29186856, 2017).
cancer (673 papers, 1995 to 2026). A tumor composed of atypical neoplastic, often pleomorphic cells that invade other tissues. "Further assessment showed CDK2 was positively associated with tumor purity and cancer-associated fibroblast (CAF) infiltration, but negatively with immune score and NK cells, memory B cells, naïve B cells, and plasma cells." (PMID 41614894, 2026). "Molecular docking revealed stronginteractions of sarcorine C and salonine C with key cancer-associatedproteins (CDK2, KRAS, CYP17A1, Bcl-2, MMP-2, and NOS)." (PMID 41141772, 2025). "Dysregulation of cyclins and cyclin-dependent kinases (CDKs) is a hallmark of cancer progression, and inhibition of CDK2 has been shown to suppress XIAP (X-linked inhibitor of apoptosis protein), thereby promoting caspase-mediated apoptosis." (PMID 41323392, 2025). "CDK2 contributes to mediate cell cycle, and its aberrant activation has been implicated in the pathogenesis of various cancers, such as pulmonary 19, mammary gland 40, hepatic 41, and esophageal squamous epithelium 42 carcinogenesis." (PMID 40740234, 2025). "A study demonstrated that in cancer cells, Cdk2 can compensate for the loss of Cdk1 during mitotic entry when Cdk1 is rapidly degraded using the auxin-degron system." (PMID 40037894, 2025). "Overexpression or dysregulation of CDK2 has been strongly associated with uncontrolled cellular proliferation in various cancers, making it a promising therapeutic target." (PMID 41286335, 2025). "Overexpression of CDK2 is often associated with uncontrolled cell proliferation, a hallmark of cancer, making the inhibition of CDK2 activity a valuable therapeutic strategy." (PMID 40076766, 2025). "This study elucidated mechanisms engaged by cancer cells to evade the death program associated with anaphase catastrophe following CDK2 inhibition." (PMID 40232858, 2025). "DepMap dataset revealed that there is a relatively small subset of cancer cell lines that are vulnerable to loss of CDK2 and its catalytic partner cyclin E1." (PMID 39924553, 2025). "Dysregulation of the cyclin E/CDK2 complex, a critical hallmark of many human cancers, results from various genetic aberrations." (PMID 40227591, 2025). "CDK2 is a protein kinase essential for regulating the cell cycle, and its dysregulation is implicated in the development of various cancers, notably CRC." (PMID 40901864, 2025). "Considering the role of A-type cyclins in activating DNA-DSB repair mechanisms in collaboration with CDK2 and Ku DNA repair proteins, conofolidine rendered carcinoma cells more susceptible to DNA-damage, leading to aggravated cytotoxicity and apoptosis." (PMID 38893527, 2024). "Multipolar mitoses caused by CDK2 inhibition conferred a different fate that led to apoptosis or polynuclear cancer cells along with reduced survival of these progeny." (PMID 38031910, 2023). "One of the fundamental CDKs associated with inadequate cancer progression is the overexpression of CDK2." (PMID 37570839, 2023). "Evidence provided here implicates the disruption of centrosome stoichiometry after CDK2 antagonism as associated with the death of aneuploid cancer cells while relatively sparing normal human alveolar epithelial cells." (PMID 38031910, 2023). "We report here that CDK2 inhibition caused a prolonged duration of chromosome rings in the examined cancer cells." (PMID 38031910, 2023). "The suppressor function of p21 against cancer cells is associated with the ability of p21 to inhibit cell proliferation through the inhibition of CDK2 activity and cell growth arrest at G0/G1 phase." (PMID 37958844, 2023). "Aberrant activity of CDK2 is linked with a myriad of human cancer types, including those originating from the ovary, breast, lung, and brain." (PMID 37049714, 2023). "In 10 cancer types, high CDK2 expression was associated with poor prognosis of the patients (P < 0.05)." (PMID 34409029, 2021).